OIT3 (oncoprotein induced transcript 3)
Description:
May be involved in hepatocellular function and development.
Synonyms: LZP; FLJ39116
Tractability: Antibody: UniProt predicts a signal peptide or a membrane-spanning region.
Gene: Protein-coding gene on chromosome 10 (72,893,573 to 72,933,036, forward strand). Ensembl gene ENSG00000138315.
Subcellular location: Nucleus envelope
Gene Ontology:
Molecular function: protein binding; calcium ion binding
Cellular component: cell surface; non-collagenous component of interstitial matrix; nuclear envelope
Genetic constraint (gnomAD): Loss-of-function variants: 32 observed, 46.16 expected, observed/expected ratio (o/e) 0.69, 90% interval 0.52 to 0.93. The upper end of that interval is the gene's LOEUF score, 0.93, which puts it in group 3 of 6, group 1 being the genes least tolerant of losing a copy. Missense variants: 590 observed, 691.01 expected, observed/expected ratio (o/e) 0.85, 90% interval 0.8 to 0.91. Synonymous variants: 224 observed, 268.58 expected, observed/expected ratio (o/e) 0.83, 90% interval 0.75 to 0.93.
Homologues: Orthologues: chimpanzee OIT3 (99% identical), macaque OIT3 (99% identical), dog OIT3 (94% identical), pig OIT3 (94% identical), rat Oit3 (91% identical), mouse Oit3 (90% identical), rabbit OIT3 (89% identical), guinea pig OIT3 (89% identical), tropical clawed frog oit3 (77% identical), zebrafish oit3 (62% identical). Paralogues in human: GP2 (27% identical), UMOD (27% identical), UMODL1 (16% identical), ZPLD1 (13% identical), TECTB (11% identical).
Diseases named in the same sentence as OIT3 in open-access papers:
OIT3 is named in the same sentence as 18 diseases in open-access papers, as found by Europe PMC text mining. Sharing a sentence is not in itself a finding about the gene and the disease. The quoted sentences say what the papers report.
hepatocellular carcinoma (5 papers, 2021 to 2025). A malignant tumor that arises from hepatocytes. "Similarly, OIT3, a liver-enriched protein linked to macrophage polarization and hepatocellular carcinoma (HCC) progression, was also elevated in S3, suggesting enhanced inflammatory responses and immune infiltration in S3." (PMID 41301514, 2025). "Oncoprotein-Induced Transcript 3 Protein (OIT3) was identified as a liver-specific gene with abnormal expression in hepatocellular carcinoma (HCC)." (PMID 36132142, 2022).
liver diseases (3 papers, 2021 to 2023). "Once Oit3 was proven to be a hallmark gene of LSECs, targeting Oit3 provides us with a promising strategy to treat liver diseases with hepatic vasculature disorders." (PMID 37696816, 2023). "Subsequently, Oit3-CreERT2 transgenic mice were generated to investigate the complexity of LSECs in liver diseases, including sinus obstructive syndrome (SOS), providing insights into the intricate relationships between liver disease and systemic conditions." (PMID 38155961, 2023). "The establishment of Oit3-CreERT2-tdTomato mice provides a valuable model for studying the complexities of LSECs in liver diseases." (PMID 37696816, 2023).
steatosis (2 papers, 2023 to 2025). Increased lipid within the cytoplasm of cells. "The zonation characteristics of OIT3 in liver pathologies, including steatosis, fibrosis, and hepatic regeneration, necessitate additional corroboration." (PMID 37696816, 2023). "Specifically, H4C1, OIT3, ANPEP, CCDC25 and KLHL41 were identified as potential biomarkers for steatosis, GP1BA as a candidate marker for MASH and C7, IGHD and GNB1 as potential biomarkers for fibrosis severity." (PMID 41301514, 2025).
Crohn disease (1 paper, 2021). A gastrointestinal disorder characterized by chronic inflammation involving all layers of the intestinal wall, noncaseating granulomas affecting the intestinal wall and regional lymph nodes, and transmural fibrosis. "Some ICGs, such as BDH2, CYP4V2, OIT3, PLD1 and SLC25A23, were reported as differentially expressed in ileum tissue from Crohn’s disease vs. non-inflammatory bowel disease control." (PMID 34098982, 2021).
gout (1 paper, 2020). A condition characterized by painful swelling of the joints, which is caused by deposition of urate crystals. "Certainly these results support further continued research about the role of LRP1 and OIT3 in gout susceptibility." (PMID 32569156, 2020). "The rare occurrence of the 2 sequence variants associated with gout within a single family and the inheritance pattern over 5 generations within that family provide both support and potential insight about the relevance of LRP1(rs767716691) and OIT3(rs554643826) to gout." (PMID 32569156, 2020). "The rare sequence variants in low-density lipoprotein receptor-related protein 1 (LRP1) and oncoprotein induced transcript 3 (OIT3) may have contributed to inheritance of gout within the 5 generations of family members in this study." (PMID 32569156, 2020). "It is possible these 2 mutations of low-density lipoprotein receptor-related protein 1 (LRP1) and oncoprotein induced transcript 3 (OIT3) could contribute to the development of gout in the direct descendants." (PMID 32569156, 2020). "Two rare, highly detrimental variants, LRP1(rs767716691) and OIT3(rs554643826) were detected in 6 direct descendants, although 1 of the 6 descendants (IV-3) has not been diagnosed with gout." (PMID 32569156, 2020).
hyperuricemia (1 paper, 2013). An abnormally high level of uric acid. "Consistently, it was reported that OIT3 deficiency impaired uric acid reabsorption in renal tubule, indicating that OIT3 over-expression might stimulate urate reabsorption and subsequently result in hyperuricemia." (PMID 23899832, 2013). "Moreover, THP co-localized with OIT3 in the renal thick ascending limb of Henle’s loop was a useful marker of renal dysfunction in hyperuricemia, as demonstrated by some findings that mutations in THP gene lead to familial juvenile hyperuricemic nephropathy and develop kidney dysfunction in mice." (PMID 23899832, 2013).
tumor (6 papers, 2021 to 2025). "Low expression of CD86+, overexpression of CD206+, and oncoprotein-induced transcript 3 (OIT3) in TAMs are significantly associated with tumor invasion abilities such as multifocal tumors and late-stage tumor lymph node metastasis (TNM)." (PMID 37663266, 2023). "In contrast, FCN3 and OIT3 were commonly downregulated, both known for their tumor-suppressive and immune-regulatory functions, highlighting their potential as universal biomarkers or therapeutic targets." (PMID 41216224, 2025). "Since OIT3 was lowly expressed in tumor cells, we overexpressed OIT3 with a lentivirus vector in various HCC cell lines." (PMID 36132142, 2022). "Meanwhile, fewer Ki-67-positive cells were observed in tumor tissues from the OIT3 overexpression group compared to the control group." (PMID 36132142, 2022). "In the present study, OIT3 significantly inhibited the growth of tumor cells in vitro and in vivo." (PMID 36132142, 2022). "Our results suggested that OIT3 functions as a tumor suppressor gene by mediating ferroptosis in HCC cells, thus providing a novel mechanism for the OIT3’s regulation in cancer progression." (PMID 36132142, 2022). "In conclusion, tumor-infiltrating immune cells may affect the clinical consequences of LINC00114/UMODL1 and LINC00114/OIT3 axes in COAD." (PMID 35847359, 2022).
cancer (4 papers, 2017 to 2024). A tumor composed of atypical neoplastic, often pleomorphic cells that invade other tissues. "The OIT3 gene in humans is mainly expressed in the liver, small intestine, and duodenum, and its functions are related to the metabolism of macrophages and cancer progression." (PMID 39795948, 2024). "Depending on the CCLE, UMODL1 and OIT3 were low in various cancer cell lines, including COAD cell lines." (PMID 35847359, 2022). "The GEPIA database was used to evaluate UMODL1 and OIT3 expression in human cancer." (PMID 35847359, 2022). "A comprehensive analysis of gene expression found novel genes related to CRC, including OIT3, which may be a new marker for this cancer." (PMID 35847359, 2022). "Genes characteristic of cancer cells – Oit3, Tnxb, Zfr2, VpreB3, Trim40." (PMID 28031533, 2017).
OIT3 also shares sentences with these, for which no sentence is quoted: atherosclerosis (1 paper); Hepatic steatosis (1); hyperlipemia (1); hypertriglyceridemia (1); inflammatory bowel disease (1); liver cancer (1); metabolic syndrome (1); nonalcoholic fatty liver (1); Obesity (1); rheumatoid arthritis (1).